F12 (coagulation factor XII)
Description:
Factor XII is a serum glycoprotein that participates in the initiation of blood coagulation, fibrinolysis, and the generation of bradykinin and angiotensin. Prekallikrein is cleaved by factor XII to form kallikrein, which then cleaves factor XII first to alpha-factor XIIa and then trypsin cleaves it to beta-factor XIIa. Alpha-factor XIIa activates factor XI to factor XIa.
Synonyms: HAF; HAE3; HAEX
Tractability: Small molecule: an approved drug acts on it; a structure with a bound ligand is known; a high-quality ligand is known; it belongs to a druggable protein family. Antibody: its Gene Ontology location is reachable by antibodies, with high confidence; UniProt places it where antibodies can reach, with medium confidence; UniProt predicts a signal peptide or a membrane-spanning region. PROTAC: its protein half-life has been measured; a small molecule that binds it is known. Other modalities: an approved drug acts on it.
Target class: Serine protease; Enzyme; Serine protease PA clan; Serine protease S1A subfamily; Protease
Gene: Protein-coding gene on chromosome 5 (177,402,133 to 177,416,583, reverse strand). Ensembl gene ENSG00000131187.
Subcellular location: Secreted
Pathways (Reactome):
Disease: Aggregated β-amyloid induces FXII autocatalysis; Defective SERPING1 causes hereditary angioedema; Defective factor XII causes hereditary angioedema
Immune System: FXIIa activates plasma kallikrein-kinin system; Regulation of FXIIa and plasma kallikrein activity
Hemostasis: FXIIa, PKa-dependent activation of coagulation pathway
Gene Ontology:
Molecular function: protein binding; serine-type endopeptidase activity; misfolded protein binding; calcium ion binding; peptidase activity
Biological process: Factor XII activation; plasma kallikrein-kinin cascade; positive regulation of blood coagulation; positive regulation of fibrinolysis; positive regulation of plasminogen activation; protein autoprocessing; protein processing; response to misfolded protein; zymogen activation; blood coagulation; blood coagulation, intrinsic pathway; innate immune response; proteolysis
Cellular component: extracellular exosome; extracellular matrix; extracellular region; plasma membrane; rough endoplasmic reticulum
Genetic constraint (gnomAD): Loss-of-function variants: 72 observed, 68.09 expected, observed/expected ratio (o/e) 1.06, 90% interval 0.87 to 1.29. The upper end of that interval is the gene's LOEUF score, 1.29, which puts it in group 5 of 6, group 1 being the genes least tolerant of losing a copy. Missense variants: 811 observed, 793.45 expected, observed/expected ratio (o/e) 1.02, 90% interval 0.96 to 1.08. Synonymous variants: 373 observed, 324.18 expected, observed/expected ratio (o/e) 1.15, 90% interval 1.06 to 1.25.
Gene-disease validity (ClinGen):
ClinGen rates the evidence that F12 causes each of these diseases.
congenital factor XII deficiency (autosomal recessive): Definitive.
hereditary angioedema type 3 (autosomal dominant): Definitive. Hereditary angioedema type 3 (HAE 3) is a form of hereditary angioedema characterized by acute edema in subcutaneous tissues, viscera and/or the upper airway.
Homologues: Orthologues: chimpanzee F12 (99% identical), macaque F12 (94% identical), rabbit F12 (77% identical), guinea pig F12 (73% identical), dog F12 (73% identical), pig F12 (72% identical), rat F12 (71% identical), mouse F12 (70% identical), tropical clawed frog f12 (43% identical), zebrafish f9a (19% identical). Paralogues in human: HGFAC (39% identical), KLKB1 (22% identical), F11 (22% identical), F9 (19% identical), CFI (19% identical), F7 (18% identical), F10 (18% identical), C1R (18% identical), C1S (18% identical), C1RL (14% identical), CFD (14% identical), PRSS55 (14% identical), and 4 more.
Diseases named in the same sentence as F12 in open-access papers:
F12 is named in the same sentence as 47 diseases in open-access papers, as found by Europe PMC text mining. Sharing a sentence is not in itself a finding about the gene and the disease. The quoted sentences say what the papers report.
hereditary angioedema (8 papers, 2010 to 2026). Hereditary angioedema (HAE) is a genetic disease characterized by the occurrence of transitory and recurrent subcutaneous and/or submucosal edemas resulting in swelling and/or abdominal pain. "Hereditary angioedema due to the Thr328Lys variant in the coagulation factor XII (HAE-FXII) affects mainly women in whom the symptomatology is dependent on high estrogen levels." (PMID 33133137, 2020). "The diagnosis "hereditary angioedema with coagulation factor XII gene mutation" (HAE-FXII) requires the corresponding demonstration of the mutation." (PMID 20667118, 2010). "Hereditary angioedema due to C1 Inhibitor deficiency shares a common kinin dependency with other HAE situations: F12-HAE, PLG-HAE, KNG1-HAE, ANGPT1-HAE, and HS3ST6-HAE, but not with MYOF-HAE, U-HAE." (PMID 35958943, 2022). "In this review, we will describe the mechanisms that are responsible for bradykinin production in hereditary angioedema (HAE) and the central role that the coagulation factor XII (FXII) plays in it." (PMID 27122021, 2016).
COVID-19 (4 papers, 2021 to 2023). A disease caused by infection with severe acute respiratory syndrome coronavirus 2. "Based on our previous work in the field of vascular biology, thrombosis and inflammation, we aimed to investigate the role of neutrophil extracellular traps (NETs) and the coagulation factor XII (FXII) in COVID-19." (PMID 34000623, 2021). "Whereas some genes associated with fibrinolysis (F12 and ANXA2) showed increased expression, many were decreased in COVID-19 lung tissue relative to normal tissue." (PMID 34648357, 2021). "Garadacimab, a fully human IgG4 monoclonal antibody, inhibits the kallikrein–kinin pathway at a key initiator, activated coagulation factor XII (FXIIa), and may play a protective role in preventing the progression of COVID-19." (PMID 37000214, 2023). "We further compared coagulation factor XII (FXII) and DNase activities in plasma samples from COVID-19 patients and healthy control donors and determined NET-induced FXII activation using a chromogenic substrate assay." (PMID 34000623, 2021).
angioedema (3 papers, 2010 to 2025). Swelling involving the deep dermis, subcutaneous, or submucosal tissues, representing localized edema. "The NM_000505.3:c.-4 T > C transition in the Coagulation factor XII (F12) gene is a common polymorphism which is considered to be disease-modifier in hereditary angioedema." (PMID 37344844, 2023).
Obesity (2 papers, 2022). Accumulation of substantial excess body fat. "Some others, such as SERPINC1, coagulation factor XII (involved in contact activation pathways), and protein C (PROC), are involved in the coagulation/fibrinolysis pathways, which are known to be activated in OA, as well as in obesity." (PMID 35606786, 2022).
Stroke (2 papers, 2014 to 2016). Sudden impairment of blood flow to a part of the brain due to occlusion or rupture of an artery to the brain. "Selective and specific kinin receptor antagonists and inhibitors of plasma kallikrein and coagulation factor XII have been developed, and have already shown therapeutic efficacy in animal models of stroke and TBI." (PMID 25404891, 2014). "The coagulation factor XII (FXII)-driven contact activation system plays a central, but not yet fully defined pathogenic role in stroke development." (PMID 26815580, 2016).
acute respiratory distress syndrome (1 paper, 2024). Progressive and life-threatening pulmonary distress in the absence of an underlying pulmonary condition, usually following major trauma or surgery. "Coagulation factor XII is activated by polyphosphates released from platelets, and initiates an intrinsic coagulation cascade, which is known to be involved in the disease onset of acute respiratory distress syndrome." (PMID 39717778, 2024).
Arterial thrombosis (1 paper, 2015). The formation of a blood clot inside an artery. "Coagulation factor XII (fXII) is important for arterial thrombosis, but its physiological activation mechanisms are unclear." (PMID 25688860, 2015).
Cerebral ischemia (1 paper, 2010). Restriction of arterial blood supply to the brain associated with insufficient oxygenation to support the metabolic requirements of the tissue. "Previous studies have shown that blood coagulation factor XII (FXII)-deficient mice are protected from pathological thrombus formation during cerebral ischemia without bearing an increased bleeding tendency." (PMID 20298537, 2010).
Disseminated intravascular coagulation (1 paper, 2022). Disseminated intravascular coagulation is characterized by the widespread activation of coagulation, which results in the intravascular formation of fibrin and ultimately thrombotic occlusion of small and midsize vessels. "The coagulation factor XII activated by endotoxin can also further activate the endogenous coagulation pathway, which ultimately leads to disseminated intravascular coagulation (DIC)." (PMID 35148668, 2022).
gastric cancer (1 paper, 2022). A primary or metastatic malignant neoplasm involving the stomach. "To find out the role of hub genes in the overall survival of gastric cancer we performed a multivariate Cox regression analysis, among 21 hub genes, the eight genes (KCNJ3, CPVL, ONECUT2, SLC19A3, DDC, PRSS21, F12, and GRTP1) were designated as independent indicators of poor prognosis." (PMID 35754804, 2022).
gestational diabetes mellitus (1 paper, 2021). "F12 is a coagulation factor that plays a role in activating the coagulation pathway, which may be a potential pathological source of serious pregnancy complications (like PE) in gestational diabetes mellitus." (PMID 34697885, 2021).
hematoma (1 paper, 2024). A hematoma is a collection of blood from a vascular structure into an extravascular space. "This case study presents an individual with abdominal liposarcoma exhibiting reduced coagulation factor XII activity, who experienced sudden unconsciousness due to spontaneous acute bilateral epidural hematoma, and subsequently achieved a favorable outcome following surgical intervention." (PMID 39376687, 2024).
Hyperglycemia (1 paper, 2025). An increased concentration of glucose in the blood. "Accordingly, f12-deficient mice were found to be protected from hyperglycemia-induced kidney injury and urinary FXII levels positively correlated with kidney dysfunction in DKD." (PMID 41318746, 2025).
Insulin resistance (1 paper, 2018). Increased resistance towards insulin, that is, diminished effectiveness of insulin in reducing blood glucose levels. "It has been showed that the activity of coagulation factor XII increased in the obese individual and has strong correlation with the measures of adiposity and insulin resistance in a number of observational studies." (PMID 29868124, 2018).
ischemic stroke (1 paper, 2019). A stroke disorder caused by obstruction of blood flow to the brain, due to thrombotic (local blood clot formation) or embolic (due to a blood clot or other material traveling from another site) event. "The second study evaluated the relationship between SNPs in the coagulation factor XII gene (F12), peak thrombin generation (pTG) level, and ischemic stroke risk." (PMID 31127075, 2019).
lung adenocarcinoma (1 paper, 2025). A carcinoma that arises from the lung and is characterized by the presence of malignant glandular epithelial cells. "In lung adenocarcinoma, the upregulation of F12 may promote tumor angiogenesis and metastasis by activating endogenous coagulation pathways." (PMID 39992528, 2025).
thrombophilia (1 paper, 2023). A condition characterized by an abnormally high level of thrombi. "Moreover, the disease-specific subnetwork contains two thrombophilia-related genes present in the DisGeNet database, TGFB1 (transforming growth factor beta-1, TGFβ-1) and F12 (coagulation factor XII), which are both disease-specific variants." (PMID 37098010, 2023).
tuberculosis (1 paper, 2025). A chronic, recurrent infection caused by the bacterium Mycobacterium tuberculosis. "Our results not only confirm the important role of A2M in active tuberculosis but also uncover a regulatory network involving A2M, F12, and ECM2." (PMID 41428679, 2025).
vascular occlusion (1 paper, 2021). "One young patient had recurrent retinal and brain vascular occlusion, and the coagulation panel sequence result showed coagulation factor XII deficiency." (PMID 33820544, 2021).
tumor (8 papers, 2015 to 2025). "We found that TENM1, FN1, and F12 are highly expressed in tumor tissue, while APOD and BTNL8 have a lower expression in tumor tissue." (PMID 34221185, 2021). "F12 (Factor XII), a key factor in the blood coagulation process, has been found to be closely related to the coagulation system, angiogenesis, and inflammatory response within the tumor microenvironment." (PMID 39992528, 2025).
infection (1 paper, 2015). The state of being infected such as from the introduction of a foreign agent such as serum, vaccine, antigenic substance or organism. "Infection of cells in which KLC2 was knocked down had no discernible effect on plaque size or virus egress to the cell surface as measured by surface B5 staining and flow cytometry, despite the F12/E2 complex interacting with KLC2." (PMID 25760349, 2015).
kidney diseases (1 paper, 2023). "In addition, coagulation factor XII (F12) was a newly identified therapeutic target for kidney diseases." (PMID 36797296, 2023).
F12 also shares sentences with these, for which no sentence is quoted: acquired angioedema (1 paper); Alzheimer disease (1); autoimmune disorders (1); behavioural disorders (1); breast carcinoma (1); breast tumor (1); C1 inhibitor deficiency (1); cancer (1); chronic hepatitis B (1); heart failure (1); hematological disease (1); hypoacusis (1); hypothyroidism (1); influenza (1); lung carcinoma (1); lupus (1); melanoma (1); meningioma (1); metachromatic leukodystrophy (1); obstetric disorder (1); papillary thyroid cancer (1); preeclampsia (1); prostate carcinoma (1); thrombosis (1); thrombotic disorders (1).